CXCL1 (C-X-C motif chemokine ligand 1)
Diseases named in the same sentence as CXCL1 in open-access papers (continued):
Sharing a sentence is not in itself a finding about the gene and the disease.
autoimmune disease (12 papers, 2006 to 2025). A disorder resulting from loss of function or tissue destruction of an organ or multiple organs, arising from humoral or cellular immune responses of the individual to their own tissue constituents. "The results showed that serum CXCL1 levels were significantly increased in patients with SLE compared with patients with other autoimmune diseases, including SS and SSc." (PMID 34961474, 2021). "Although there are few reports that support a possible role of CXCL1 during inflammation and neovascularization in autoimmune diseases, we examined CXCL1 in SLE serum in this study." (PMID 34961474, 2021). "For the first time, we demonstrate that serum CXCL1 levels were significantly higher in patients with SLE than in patients with other autoimmune diseases and healthy controls." (PMID 34961474, 2021). "The results presented here have uncovered an essential function of TLR4 in the induction of the chemokine CXCL1/KC in an organ-specific autoimmune disease." (PMID 24586934, 2014). "Overexpression and administration of recombinant CXCL1/KC suppresses murine autoimmune diseases such as experimental autoimmune encephalomyelitis and autoimmune myocarditis; in the latter case treatment also reduced the numbers of autoreactive effector T cells specific to cardiac self-peptides." (PMID 30450101, 2018). "CXCL1/KC exerts an effective anti-inflammatory effect in a heart-specific autoimmune disease." (PMID 24586934, 2014). "CXCL1 serum concentrations were examined in 90 SLE patients, 56 other autoimmune diseases (OADs) patients and 100 healthy controls using enzyme-linked immunosorbent methodology." (PMID 34961474, 2021). "Although elevated CXCL1 expression has been reported in several human cancers, the role of CXCL1 and its receptor CXCR2 in autoimmune diseases is unclear." (PMID 34961474, 2021). "The main function of Th17 cells is to produce various cytokines, such as IL-17, IL-21 and IL-22, which stimulate epithelial cells, fibroblasts and smooth muscle cells of the airway to secrete CXCL1 and CXCL8, thereby participating in autoimmune diseases." (PMID 34863307, 2021). "Mouse keratinocyte-derived chemokine (KC, also known as the mouse IL-8 analog, CXCL1) is generally thought to be a pro-inflammatory chemokine, but may have an anti-inflammatory effect on liver inflammation in this model and other murine models of other autoimmune diseases." (PMID 30450101, 2018).
esophageal squamous cell carcinoma (12 papers, 2017 to 2025). Esophageal squamous cell carcinoma (ESCC) is a type of esophageal carcinoma (EC) that can affect any part of the esophagus, but is usually located in the upper or middle third. "Metformin reduced CXCL1 secretion in esophageal squamous cell carcinoma (ESCC) cells through enhancing AMPK phosphorylation and inducing Dachshund homolog 1 (DACH1) expression." (PMID 33613512, 2020). "LAMC1 secretion was associated with the formation of inflammatory CAFs in esophageal squamous cell carcinoma, and upregulation of LAMC1 expression promoted CXCL1 secretion, which stimulated inflammatory CAFs via CXCR2-pSTAT3 and thus promoted tumor progression." (PMID 37588985, 2023). "Overproduced CXCL1 then induces radioresistance in esophageal squamous cell carcinoma." (PMID 34895039, 2021). "In addition, CAFs-derived CXCL1 mediated radioresistance in esophageal squamous cell carcinoma, providing that CXCL1 can be an attractive target to reverse tumor radioresistance." (PMID 29360827, 2018). "An increase in CXCL1 expression in the tumor is also observed under the influence of ionizing radiation, mainly due to an increase in the expression of this chemokine and CXCR2 in cancer-associated fibroblasts (CAF), as shown by experiments on esophageal squamous cell carcinoma." (PMID 40427171, 2025). "LAMC1 promoted CXCL1 secretion, which stimulated inflammatory CAF formation via CXCR2-pSTAT3, which in turn accelerates esophageal squamous cell carcinoma progression." (PMID 36246404, 2022). "CXCL1 also decreases the expression of superoxide dismutase 1 (SOD1) in cancer cells, as shown by experiments on esophageal squamous cell carcinoma cells, which results in increased levels of ROS in the tumor cell and thus increased activity of DNA damage repair enzymes." (PMID 40427171, 2025). "Although not yet studied in BCa, metformin treatment was found to inhibit CXCL1 in head and neck squamous cell carcinoma (HNSCC) and esophageal squamous cell carcinoma (ESCC), suggesting a possible chemokine-mediated mechanism in metformin’s effect in BCa." (PMID 39409924, 2024). "Notably, in esophageal squamous cell carcinoma (ESCC), TGF-β1-induced LAMC1 expression promotes CXCL1 secretion, which in turn activates the AKT-NFκB signaling axis, leading to the formation of inflammatory CAFs (iCAFs)." (PMID 40490643, 2025).
Insulin resistance (12 papers, 2011 to 2025). Increased resistance towards insulin, that is, diminished effectiveness of insulin in reducing blood glucose levels. "Through the chemokine and cytokine receptor interaction pathways, CXCL1 establishes crosstalk between cancer cells and inflammatory cells, ultimately supporting cellular environments where both insulin resistance and cancer cell invasiveness can thrive." (PMID 40127075, 2025). "Human and animal studies have shown CXCR1/2 agonists (e.g., CXCL8, CXCL5 in T1D patients, CXCL1 in mice) to be correlated with obesity and insulin resistance." (PMID 40718478, 2025). "In turn, CXCL1/2 recruit neutrophils and macrophages to adipose tissue, where they promote insulin resistance." (PMID 34686752, 2021). "CRTC2/3 promote insulin resistance via induction of the chemokines CXCL1/2." (PMID 34686752, 2021). "We wondered whether CXCL1/2 expression is sufficient to promote glucose intolerance and insulin resistance." (PMID 34686752, 2021). "Based on the effects of CXCL1/2 immuno-neutralization on insulin signaling, we employed CXCL1 KO mice to evaluate whether this chemokine contributes to HFD-induced insulin resistance." (PMID 34686752, 2021). "Based on the proposed effects of CRTC2/3 on CXCL1/2 expression and insulin resistance, we evaluated whether depletion of CRTC2/3 in adipose tissue modulates the effects of HFD on insulin signaling and glucose metabolism." (PMID 34686752, 2021). "Collectively, these results indicate that the induction of CXCL1/2 by CRTC2/3 in adipose tissue during HFD feeding, contributes in part to the development of insulin resistance." (PMID 34686752, 2021). "Cxcl1/KC stimulates the infiltration of neutrophils into WAT and represents the mouse ortholog of human interleukin-8, but the exact role of this factor in the pathogenesis of insulin resistance remains to be established." (PMID 24086498, 2013).
osteosarcoma (12 papers, 2012 to 2024). A usually aggressive malignant bone-forming mesenchymal neoplasm, predominantly affecting adolescents and young adults. "Osteosarcoma tumors have a lower pH, as do many other cancers; this causes an increase in the expression of many chemokines and cytokines, including CXCL1 in MSCs." (PMID 38673949, 2024). "CXCL1 expression in osteosarcoma cancer cells is dependent on the factors highly expressed in most tumors of this cancer." (PMID 38673949, 2024). "Many factors that play significant roles in neutrophil migration have been explored in osteosarcoma, including CXCL1, IL-6, CCL2, and so on." (PMID 39582869, 2024). "In osteosarcoma, CXCL1 is known to upregulate the expression of NF-κB via the CXCR2/FAK/PI3K/Akt pathway." (PMID 36614235, 2023). "The CXCL1 overexpression has a positive relationship with the migration and invasive activity of osteosarcoma cell lines." (PMID 35281077, 2022). "The in vivo animal model further demonstrated that CXCL1 serves as a critical promoter in osteosarcoma metastasis to the lung." (PMID 34760697, 2021). "In this study, overexpression of CXCL1 has a positive correlation with the migratory and invasive activities in osteosarcoma cell lines." (PMID 34760697, 2021). "Our findings demonstrate the cascade mechanism regulating the network in lung metastasis osteosarcoma, therefore indicating that the CXCL1/CXCR2 pathway is a worthwhile candidate to further develop treatment schemas." (PMID 34760697, 2021). "The IHC results revealed higher levels of CXCL1 and VCAM-1 expression in patients with a higher-grade osteosarcoma than in those with a lower-grade osteosarcoma; the levels of CXCL1 and VCAM-1 expression were reflected by the tumor stage (–C)." (PMID 34760697, 2021). "In the current study, our in vitro and in vivo studies showed that CXCL1 directly facilitates cell migration and invasion abilities, and metastasis nodule formation to the lung in osteosarcoma." (PMID 34760697, 2021). "MG63 has a rapid cell migration ability compared to other osteosarcoma cell lines; furthermore, the CXCL1 expression levels were also consistent with the trend of migration ability." (PMID 34760697, 2021). "Hypoxia and interstitial acidosis are also important in the promotion of osteosarcoma bone metastasis, in part through activation of IL-8, IL-6, NF-κB1, colony-stimulating factors CSF2 and CSF3, BMP-2, CCL5, CXCL5 and CXCL1 in tumor-associated MSCs." (PMID 34831167, 2021). "A recent study suggested that CXCL1 secreted from human pulmonary artery endothelial cells played a homing role for osteosarcoma metastasis to the lung." (PMID 34760697, 2021). "The result of the study firmly indicates that the CXCL1/CXCR2 is an essential axis for metastasis of osteosarcoma." (PMID 34760697, 2021). "According to these results, the expression of CXCL1 showed a positive regulation on the migratory, wound healing, and invasive abilities in osteosarcoma cells." (PMID 34760697, 2021). "HPAECs CM pretreated with CXCL1 antibody significantly inhibited recruitment and the migratory ability of osteosarcoma cells." (PMID 32079335, 2020). "High levels of CXCL1 secreted by human pulmonary artery endothelial cells (HPAECs) promoted osteosarcoma cell mobility, which was mediated by the upregulation of VCAM-1 expression." (PMID 32079335, 2020). "We are the first to provide evidence showing that HPAECs-induced secretion of CXCL1 recruits CXCR2-expressing osteosarcoma cells to pre-metastatic pulmonary sites." (PMID 32079335, 2020). "Human pulmonary artery endothelial cells secrete CXCL1, thus promoting the migration and homing of osteosarcoma cells to the lung." (PMID 32079335, 2020). "Our data show that HPAECs-secreted CXCL1 directs the homing of osteosarcoma cells to the lung, thus promoting lung metastasis in osteosarcoma." (PMID 32079335, 2020).
osteosarcoma (continued). "In an in vivo lung metastasis model of osteosarcoma, lung blood vessels expressed CXCL1 and osteosarcoma cells expressed the CXCR2 receptor." (PMID 32079335, 2020). "Our findings illustrate a molecular mechanism of lung metastasis in osteosarcoma and indicate that CXCL1/CXCR2 is worth targeting in treatment schemas." (PMID 32079335, 2020). "This evidence suggests that the CXCL1/CXCR2 axis plays a pivotal role in osteosarcoma lung metastasis." (PMID 32079335, 2020). "CXCL1 expression is higher in osteosarcoma tumors than in healthy tissue." (PMID 38673949, 2024). "A positive correlation observed between the CXCL1 and VCAM-1 staining intensity of the human osteosarcoma tissue (r2 = 0.562) indicated that the levels of these proteins were associated with the progression of osteosarcoma." (PMID 34760697, 2021). "Next, CXCL1 (1–10 ng/ml) was applied to investigate whether CXCL1 expression influences cell motility in these three osteosarcoma cell lines." (PMID 34760697, 2021). "To determine whether the CXCL1/CXCR2 axis is involved in osteosarcoma lung metastasis, we examined the expression of CXCL1 in human pulmonary artery endothelial cells (HPAECs), which reside in pulmonary vasculature, where metastatic foci are found." (PMID 32079335, 2020). "Here, we show that the CXCL1/CXCR2 paracrine axis is crucial for lung metastasis in osteosarcoma." (PMID 32079335, 2020). "We found that HPAECs-induced secretion of CXCL1 promoted VCAM-1 expression in osteosarcoma cells, which suggests that VCAM-1 may assist with the transendothelial migration of cancer cells." (PMID 32079335, 2020). "HPAECs-secreted CXCL1 activates PI3K/Akt signaling in osteosarcoma cells." (PMID 32079335, 2020). "In consideration of the fact that HPAECs-secreted CXCL1 recruits osteosarcoma cells and contributes to lung metastasis, and our findings showing that VCAM-1 expression is positively correlated with CXCR2 in osteosarcoma tissue, we analyzed VCAM-1 expression after HPAECs CM treatment." (PMID 32079335, 2020). "However, although the pro-metastatic functions of CXCL1 are recognized in tumor progression, its role remains unclear in osteosarcoma." (PMID 32079335, 2020). "Prominently, we observed persistently elevated levels of eotaxin/CCL11, CCL2, CCL7, CXCL1, CXCL10 and BAFF in the DIPG, ALL, and aggressive osteosarcoma models, the same three models that also exhibit cognitive deficits." (PMID 38798554, 2024). "The correlated expression of CXCL1 and VCAM-1 was observed in the immunohistochemistry staining from human osteosarcoma specimens." (PMID 34760697, 2021). "We next examined levels of CXCL1 and VCAM-1 expression in osteosarcoma specimens, to determine the prognostic relevance of CXCL1 and VCAM-1 in osteosarcoma progression." (PMID 34760697, 2021). "Inhibitors of FAK (FAKi), PI3K (LY294002 and wortmannin), Akt (Akti), and NF-κB (TPCK and PDTC) were applied and showed a clear suppression pattern of CXCL1-triggered cell migration and VCAM-1 mRNA expression in MG63 osteosarcoma cells." (PMID 34760697, 2021). "However, the role and related mechanisms of CXCL1 in osteosarcoma remain unclear." (PMID 34760697, 2021). "Our results suggested that CXCL1 via the CXCR2/FAK/PI3K/Akt/NF-κB pathway enhanced VCAM-1 expression to assist the migratory and invasive activity in osteosarcoma cells." (PMID 34760697, 2021). "Recently, CXCL1 and CXCR2 have been crucial indicators for lung metastasis in osteosarcoma by paracrine releases, suggesting the involvement of directing neutrophils into tumor microenvironment." (PMID 34760697, 2021). "Our investigation suggests that CXCL1/CXCR2, as a therapeutic candidate, can be targeted to further develop medicine to suppress or prevent the metastatic spread of osteosarcoma." (PMID 34760697, 2021). "The paracrine CXCL1/CXCR2 network links HPAECs and osteosarcoma cells, provides a metastatic trace for the cells, and directs their destination." (PMID 32079335, 2020).
osteosarcoma (continued). "As osteosarcoma cells contain high levels of CXCR2, a chemokine receptor of CXCL1, their response to HPAECs secretion of CXCL1 promotes lung metastasis." (PMID 32079335, 2020). "Preincubation of HPAECs CM with CXCL1 neutralized antibody reversed VCAM-1 expression, demonstrating that HPAECs-secreted CXCL1 can directly stimulate VCAM-1 expression in osteosarcoma cells." (PMID 32079335, 2020). "In addition, osteosarcoma cells attract normal bone marrow MSCs to the tumor stroma via secretion of CCL2, CXCL1 and TGF-β, supporting their trans-differentiation into cancer-associated fibroblasts (CAFs)." (PMID 34831167, 2021). "Although ICAM-1 has also been shown to play roles during the initiation of the metastatic cascade driving tumor progression, this development seems to not involve the CXCL1-triggered metastatic cascade in osteosarcoma cells." (PMID 34760697, 2021). "Furthermore, our data demonstrated that PTEN knockdown diminishes the growth-inhibitory effect and rescues the down-regulated genes, such as IL-6, PDGF8, CXCL1 and CXCL817, 18, after silencing FGD1 in osteosarcoma tumor cells." (PMID 32194840, 2020). "Finally, the CXCR2 chemical inhibitor SB225002 and CXCR2 shRNA confirmed that the CXCL1/CXCR2 axis is required for VCAM-1 expression and mobility of osteosarcoma cells." (PMID 32079335, 2020). "To validate whether HPAECs-secreted CXCL1 plays a major role in osteosarcoma homing and migration, we used CXCL1 neutralizing antibody to block the CXCL1/CXCR2 interaction between HPAECs and osteosarcoma cells." (PMID 32079335, 2020). "The strategy to suppress the expression level of CXCL1 could effectively decrease the VCAM-1 expression, which has the beneficial response for inhibiting migration, invasion, and wound healing abilities in osteosarcoma." (PMID 34760697, 2021). "The current study showed that the CXCL1 could signal the CXCR2/focal adhesion kinase (FAK)/phosphatidylinositol-3-kinase (PI3K)/Akt/nuclear factor-kappa B (NF-κB) pathway to increase VCAM-1 expression and subsequently upregulate the metastasis ability of human osteosarcoma cells." (PMID 34760697, 2021).